NF1 (neurofibromin 1)
Description:
Stimulates the GTPase activity of Ras. NF1 shows greater affinity for Ras GAP, but lower specific activity. May be a regulator of Ras activity.
Synonyms: NFNS; VRNF; WSS
Tractability: Small molecule: a structure with a bound ligand is known; it has a high-quality binding pocket. Antibody: UniProt places it where antibodies can reach, with high confidence; its Gene Ontology location is reachable by antibodies, with high confidence; the Human Protein Atlas places it where antibodies can reach. PROTAC: UniProt records ubiquitination sites on it; ubiquitination databases record sites on it; its protein half-life has been measured.
Gene: Protein-coding gene on chromosome 17 (31,094,927 to 31,382,116, forward strand). Ensembl gene ENSG00000196712.
Subcellular location: Nucleus; Nucleus, nucleolus; Cell membrane
Subcellular location (Human Protein Atlas): Plasma membrane; Microtubules; Nucleoplasm
Pathways (Reactome):
Disease: RAS signaling downstream of NF1 loss-of-function variants
Signal Transduction: Regulation of RAS by GAPs
Gene Ontology:
Molecular function: GTPase activator activity; phosphatidylcholine binding; phosphatidylethanolamine binding; protein binding
Biological process: cognition; negative regulation of cell migration; negative regulation of endothelial cell proliferation; negative regulation of MAPK cascade; positive regulation of GTPase activity; regulation of angiogenesis; regulation of blood vessel endothelial cell migration; actin cytoskeleton organization; adrenal gland development; artery morphogenesis; brain development; camera-type eye morphogenesis; cell communication; cerebral cortex development; collagen fibril organization; extracellular matrix organization; forebrain astrocyte development; forebrain morphogenesis; heart development; liver development; MAPK cascade; metanephros development; myelination in peripheral nervous system; negative regulation of fibroblast proliferation; negative regulation of neuroblast proliferation; and 20 more
Cellular component: axon; dendrite; membrane; nucleoplasm; plasma membrane; cytoplasm; cytosol; nucleus; nucleolus
Genetic constraint (gnomAD): Loss-of-function variants: 109 observed, 284.45 expected, observed/expected ratio (o/e) 0.38, 90% interval 0.33 to 0.45. The upper end of that interval is the gene's LOEUF score, 0.45, which puts it in group 1 of 6, group 1 being the genes least tolerant of losing a copy. Missense variants: 2,018 observed, 3,353.9 expected, observed/expected ratio (o/e) 0.6, 90% interval 0.58 to 0.62. Synonymous variants: 1,052 observed, 1,180.3 expected, observed/expected ratio (o/e) 0.89, 90% interval 0.85 to 0.94.
Gene-disease validity (ClinGen):
ClinGen rates the evidence that NF1 causes each of these diseases.
neurofibromatosis type 1 (autosomal dominant): Definitive. A clinically heterogeneous, neurocutaneous genetic disorder characterized by cafe-au-lait spots, iris Lisch nodules, axillary and inguinal freckling, and multiple neurofibromas.
familial ovarian cancer (autosomal dominant): No Known Disease Relationship. An instance of ovarian cancer that is caused by an inherited modification of the individual's genome.
Cancer hallmarks: escaping programmed cell death (suppresses); angiogenesis (suppresses); invasion and metastasis (suppresses); suppression of growth (promotes)
Homologues: Orthologues: chimpanzee NF1 (99% identical), macaque NF1 (99% identical), dog NF1 (99% identical), pig NF1 (99% identical), rabbit NF1 (99% identical), rat Nf1 (99% identical), mouse Nf1 (98% identical), guinea pig NF1 (95% identical), tropical clawed frog nf1 (90% identical), zebrafish nf1b (85% identical), zebrafish nf1a (85% identical), Drosophila melanogaster Nf1 (56% identical). Paralogues in human: RASA3 (8% identical), RASA2 (8% identical), RASA4 (8% identical), RASA4B (8% identical), RASAL1 (7% identical), RASAL2 (7% identical), DAB2IP (6% identical), RASA1 (6% identical), RASAL3 (5% identical).
Diseases named in the same sentence as NF1 in open-access papers:
NF1 is named in the same sentence as 794 diseases in open-access papers, as found by Europe PMC text mining. Sharing a sentence is not in itself a finding about the gene and the disease. The quoted sentences say what the papers report.
neurofibromatosis type 1 (614 papers, 2005 to 2026). "In neurofibromatosis type 1 (NF1), loss-of-function mutations in the NF1 gene increase activation of the RAS-MEK-ERK signaling cascade, driving tumorigenesis." (PMID 42116118, 2026). "Neurofibromatosis type 1 (NF1) is an autosomal dominant condition in which patients are heterozygous for a disruptive pathogenic variant in the NF1 gene." (PMID 41564118, 2026). "Plexiform neurofibromas associated with neurofibromatosis type I (pNF1s) are benign tumors caused by the complete loss of function of the NF1 gene, which encodes a negative regulator of the RAS/mitogen-activated protein kinase (MAPK) pathway." (PMID 41827868, 2026). "Neurofibromatosis type 1 (NF1) is an autosomal dominant syndrome caused by mutations in the NF1 gene." (PMID 41540280, 2026). "In Neurofibromatosis type I (NF1)-deficient malignant peripheral nerve sheath tumor (MPNST) cells, HSF1 loss induces widespread protein polyubiquitination, aggregation, and tumor-suppressive amyloidogenesis, yet is dispensable in non-transformed Schwann cells." (PMID 41835397, 2026). "Neurofibromatosis type 1 (NF1) is an inherited autosomaldominant disorder caused by various heterogeneous alterations in the NF1 gene, which encodes the protein neurofibromin and thus exerts a significant regulatory effect on the RAS signal pathway." (PMID 41528496, 2026). "The two monozygotic twin pairs concordant for hippocampal sclerosis had clinical neurofibromatosis type 1 with pathogenic germline NF1 variants." (PMID 40577228, 2025). "Mutations in the NF1 gene cause Neurofibromatosis Type 1 (NF1), one of the most common genetic disorders." (PMID 41374990, 2025). "NF-1, also known as von Recklinghausen’s disease, is an autosomal dominant inherited disorder that causes various lesions in multiple organs, including the skin and the nervous, ocular, and skeletal systems." (PMID 40861330, 2025). "In this study of NF1 mutations in individuals with neurofibromatosis type 1, we observed independent second NF1 hits in macroscopically and histologically normal pediatric and adult tissues." (PMID 40000831, 2025). "Germline NF1 mutation is associated with neurofibromatosis type 1, characterized by the development of neurofibromas." (PMID 41170454, 2025). "The MEK inhibitor selumetinib is FDA approved for treating nervous system tumors in patients with syndromic neurofibromatosis type 1 (NF-1) harboring a germline NF1 mutation." (PMID 40985888, 2025). "Neurofibromatosis type 1 (NF1) is a genetic disorder caused by mutations of the NF1 tumor suppressor gene resulting in the loss of function of neurofibromin, a GTPase-activating protein (GAP) for Ras." (PMID 40590220, 2025). "Half of all MPNSTs develop sporadically, while the other half arise in patients with neurofibromatosis Type 1 (NF1), a tumor-prone, neurological syndrome caused by germline mutations in the NF1 gene." (PMID 40723291, 2025). "Neurofibromatosis type 1 (NF1) is an autosomal dominant disorder caused by mutations in the NF1 gene, typically diagnosed during early childhood and characterized by significant phenotypic heterogeneity." (PMID 40428382, 2025). "NF1 encodes the multifunctional tumor suppressor protein, neurofibromin, which is best known for its causative role in neurofibromatosis type 1 and in regulating MAPK signaling." (PMID 39804140, 2025). "Here we performed whole-genome and whole-exome sequencing on 479 tissue biopsies from a child with neurofibromatosis type 1, a multisystem cancer-predisposing syndrome mediated by constitutive monoallelic NF1 inactivation." (PMID 40000831, 2025). "In neurofibromatosis type 1, downregulation of neurofibromin expression due to loss of function mutations of NF1 breaks down the Ras-Raf-MAPK signaling pathway and thus results in an enhanced mitotic signaling of ECs." (PMID 40508049, 2025).
neurofibromatosis type 1 (continued). "Neurofibromatosis type 1 (NF1) is a multisystem genetic disorder with autosomal dominant inheritance, caused by mutations in the NF1 gene on chromosome 17q11.2." (PMID 40625468, 2025). "Loss of the Ras GTPase activating protein (GAP) neurofibromin encoded by the NF1 gene causes the congenital cancer predisposition syndrome neurofibromatosis type-1 (NF-1)." (PMID 40587782, 2025). "Neurofibromatosis type 1 occures due to germline mutation in the NF1 gene, which is located at 17q11.2." (PMID 39654560, 2025). "Neurofibromatosis type 1 (NF1), also known as von Recklinghausen disease, is a genetic disorder linked to NF1 tumor suppressor gene mutations." (PMID 39722043, 2025). "Neurofibromatosis type 1 (NF1) is a rare genetic condition with an autosomal dominant inheritance pattern, caused by germline mutations in the NF1 tumor suppressor gene." (PMID 41216676, 2025). "Neurofibromatosis type 1 is a common genetic disorder caused by loss-of-function mutations in the NF1 gene." (PMID 41374990, 2025). "Neurofibromatosis Type 1 (NF1) is a rare autosomal dominant disorder caused by mutations or deletions in the NF1 gene, with approximately 5% to 11% of cases specifically attributed to the 17q11.2 microdeletion." (PMID 40225101, 2025). "The NF1 c.888+2T>C variant is a poignant example as neurofibromatosis type-1 is a high penetrance disease caused only by pathogenic variants in NF1." (PMID 41300834, 2025). "Both twin pairs have a clinical and genetic diagnosis of neurofibromatosis type 1 (NF1) with pathogenic germline variants in NF1 (NF1 c.3826 C > T p.Arg1276Ter and NF1 c.2125T > C p.Cys709Arg)." (PMID 40577228, 2025). "Neurofibromatosis type 1 (NF1) is a genetic disorder affecting up to 1:2000 births, which is caused by heterozygous pathogenic variants or deletions of the NF1 gene." (PMID 39340758, 2025). "Neurofibromatosis type 1 (NF-1), also known as von Recklinghausen disease, is an autosomal dominant neurocutaneous disorder caused by loss-of-function mutations in the NF-1 gene." (PMID 40416267, 2025). "Neurofibromatosis type 1 (NF1) is an autosomal dominant tumor predisposition syndrome caused by pathogenic variants in the NF1 gene, with an estimated prevalence of 1/4,000 to 1/2,000 individuals without significant racial or gender predilection." (PMID 40895107, 2025). "Plexiform neurofibroma (pNF) is one of the most clinically challenging manifestations of neurofibromatosis type 1 (NF1), a genetic disorder caused by the biallelic loss of the NF1 tumor suppressor gene." (PMID 40723243, 2025). "Pathogenic variants in the NF1 gene (autosomal-dominant with full penetration) cause neurofibromatosis 1 type (NF1)." (PMID 41300842, 2025). "Other examples include MEF2C (NM_002397.5:c.-66A > T) and NF1 (NM_001042492.3:c.-280C > T), where uoORF-creating variants were found to cause severe developmental disorders and neurofibromatosis type I, respectively." (PMID 40610610, 2025). "Neurofibromatosis type 1 (NF1), also known as von Recklinghausen's disease, is an autosomal dominant neurocutaneous disorder caused by mutations in the NF1 gene located on chromosome 17q11.2." (PMID 40951077, 2025). "Neurofibromatosis type 1 (NF1) is an autosomal dominant genetic disorder caused by the heterozygous loss of the NF1 gene, resulting in overactivation of the RAS signaling pathway." (PMID 40684195, 2025). "Multiple lines of evidence arrive at the same conclusion: in neurofibromatosis type 1, nonsynonymous second somatic mutations of NF1 are selected for in histologically normal tissues." (PMID 40000831, 2025). "Neurofibromatosis type 1 is caused by heterozygous loss-of-function mutations in the gene encoding NF1, the most critical RAS-GAP by disease association, while both KRAS and NRAS mutations were described to cause Noonan syndrome." (PMID 41248180, 2025).
neurofibromatosis type 1 (continued). "An attenuated phenotype from that in neurofibromatosis type 1 is seen in the very rare Legius syndrome, where the gene of the NF1-recruiting SPRED1 is mutated." (PMID 41248180, 2025). "Neurofibromatosis type 1 (NF1) is an autosomal dominant genetic condition caused by pathogenic variants in the NF1 tumor suppressor gene." (PMID 40471421, 2025). "Neurofibromatosis type 1 (NF1) is an autosomal dominant genetic disorder caused by mutations in the NF1 gene (17q11.2), leading to a wide spectrum of systemic manifestations, with predominant, though not exclusive, involvement of the nervous system." (PMID 40565537, 2025). "Neurofibromatosis type 1 (NF1) is an autosomal dominant neurocutaneous disorder resulting from pathogenic variants in the NF1 gene." (PMID 41357572, 2025). "Neurofibromatosis type 1 (NF1) is a genetic disorder affecting 1 in 3 000 people due to heterozygous mutations in the NF1 gene." (PMID 41397954, 2025). "Neurofibromatosis type 1 (NF1) is an autosomal dominant genetic disorder caused by mutations in the NF1 gene, encoding the tumor suppressor neurofibromin." (PMID 40568288, 2025). "Neurofibromatosis type 1 (NF1) is an autosomal dominant disorder caused by mutations in NF1, with a global incidence of approximately 1 in 3,000 live births." (PMID 40630199, 2025). "Overall, truncating NF1 mutations were under positive selection in normal tissues from individuals with neurofibromatosis type 1." (PMID 40000831, 2025). "Neurofibromatosis type 1 (NF1) is an autosomal dominant disorder stemming from mutations in the NF1 gene on chromosome 17q11.2, which leads to a hyperactive RAS signaling pathway." (PMID 39335500, 2024). "Neurofibromatosis type 1 (NF1) is an autosomal dominant disorder resulting from mutations in the NF1 gene." (PMID 39335500, 2024). "Neurofibromatosis type 1 (NF1) is the most common genetic disorder caused by NF1 gene mutations that encode neurofibromin, which is ubiquitously expressed." (PMID 38481529, 2024). "Spontaneous VVFs were observed in 64.3% of the cases, including three associated with neurofibromatosis type 1 (NF-1)." (PMID 38396452, 2024). "Neurofibromatosis Type 1 (NF1) is an autosomal dominant hereditary condition caused by germline pathogenic variants in the NF1 gene." (PMID 38539455, 2024). "Neurofibromatosis type 1 (NF1) is a rare tumor-predisposition syndrome that affects approximately 1 in 3500 persons and is caused by heterozygous loss of the NF1 gene." (PMID 38691597, 2024). "Neurofibromatosis type 1 (NF1) is a hereditary autosomal dominant disorder caused by mutation of the NF1 gene, which produces the neurofibromin protein." (PMID 38785480, 2024). "Neurofibromatosis type 1 (NF1) is a genetic disorder that is caused by mutations in the NF1 tumor-suppressor gene." (PMID 39004713, 2024). "Neurofibromatosis type 1 (NF1) microdeletion syndrome is caused by a heterozygous deletion of 17q11.2 region, encompassing NF1 gene and accounting for 4.7–11% of patients affected by neurofibromatosis type-I." (PMID 38874808, 2024). "Recent studies confirmed that Schwann cells initiate neurofibroma formation and such tumors associated with neurofibromatosis 1 show a loss of NF1 gene expression and high levels of Ras." (PMID 38603731, 2024). "Pathogenic variants in NF1 cause Neurofibromatosis type 1 (NF1) or Von Recklinghausen disease, an autosomal dominant disorder with an incidence between of 1:2000-1:2800 births." (PMID 38270845, 2024). "Excluding seven children with neurofibromatosis type I and pathogenic variants in NF1, all of which were known to their oncologist, nine individuals (12%) had P/LP germline variants in high- and moderate-penetrance genes." (PMID 38755180, 2024).
neurofibromatosis type 1 (continued). "All six children with LP/P variants in the NF1 gene had a known Neurofibromatosis type 1 diagnosis; five were diagnosed with pilocytic astrocytoma of which two affecting the optic pathway; one with a high-grade astrocytoma with piloid features." (PMID 38803632, 2024). "Neurofibromatosis type 1 (NF1), or von Recklinghausen disease, is a neurogenetic disorder caused by mutations in the NF1 gene, inherited in an autosomal dominant manner." (PMID 39840093, 2024). "Neurofibromatosis type 1 (NF1) is an autosomal-dominant syndrome caused by mutations in the NF1 tumor-suppressor gene on chromosome 17." (PMID 39201967, 2024). "Here, we describe the mechanism of action of a third compound, Y102, and identify inhibition of lysosomal trafficking as a potential vulnerability of both sporadic and neurofibromatosis type I-associated NF1-deficient tumors." (PMID 39016685, 2024). "Neurofibromatosis 1, also known as von Recklinghausen’s disease, makes up 96% of all neurofibromatosis cases and is an autosomal dominant neurocutaneous disorder caused by a germline mutation in the NF1 gene." (PMID 38541874, 2024). "Neurofibromatosis type 1 is a neurocutaneous genetic disorder caused by mutations in the NF1 gene, resulting in the formation of benign tumors called neurofibromas." (PMID 38216958, 2024). "Neurofibromatosis type 1 (NF1) is an autosomal dominant neurocutaneous disorder caused by loss-of-function variants in the NF1 gene." (PMID 39001468, 2024). "For example, in neurofibromatosis type 1 patients, splicing mutations in NF1 represents the 40% of the amount of causative variants, whereas in hereditary breast/ovarian cancer, splicing aberrations in BRCA1/2 are about 49%." (PMID 39944559, 2024). "Neurofibromatosis type 1 is an autosomal dominant disease caused by an NF1 mutation, with a prevalence of 1 in 3000 births." (PMID 39015197, 2024). "In a study by Kobayashi, Matsune, and Ohashi, the occurrence of distinctive oral manifestations for cases of Neurofibromatosis type 1 (NF1) with NF1 gene deletion compared to NF1 gene mutation was clearly demonstrated." (PMID 38364341, 2024). "Neurofibromatosis type 1 (NF1), also known as von Recklinghausen’s disease, arises from mutations in the NF1 gene spanning over 350 kb on chromosome 17q11.2." (PMID 39334573, 2024). "Pathogenic variants of the NF1 are the cause of neurofibromatosis 1, an autosomal dominant condition." (PMID 39390525, 2024). "Neurofibromatosis type 1 (NF1) is one of the most common genetic disorders caused by heterozygous germline NF1 mutations." (PMID 38481529, 2024). "Neurofibromatosis type 1 (NF1) is a dominant autosomal disorder caused by mutations in the NF1 gene." (PMID 38672195, 2024). "Watson and colleagues show nonsense mutation suppression has the potential to treat the underlying cause of neurofibromatosis type 1 (NF1) in patients with NF1 nonsense mutations." (PMID 37520682, 2023). "Neurofibromatosis type 1 (NF1) is a rare chronic neurocutaneous disease caused by loss-of-function alterations in the gene NF1, encoding the tumor suppressor neurofibromin." (PMID 38136356, 2023). "Neurofibromatosis type 1 is an inherited genetic disorder characterized by cancer predisposition due to a mutation in the neurofibromin type 1 (NF1) gene coding for the neurofibromin, a tumor suppressor protein." (PMID 37046997, 2023). "As a tumor-suppressive gene, NF1 gene mutations are linked not only to neurofibromatosis type 1 but also to juvenile myelomonocytic leukemia (OMIM: 607,785), familial spinal neurofibromatosis (OMIM:162,210), and Watson syndrome (OMIM: 193,520), etc.." (PMID 37095468, 2023).